RPL5P26 (ribosomal protein L5 pseudogene 26)
Synonyms: RPL5_13_1059
Gene: Processed pseudogene on chromosome 10 (69,778,962 to 69,779,838, forward strand). Ensembl gene ENSG00000230469.
Diseases named in the same sentence as RPL5P26 in open-access papers:
RPL5P26 is named in the same sentence as 1 disease in open-access papers, as found by Europe PMC text mining. Sharing a sentence is not in itself a finding about the gene and the disease.
RPL5P26 shares sentences with these, for which no sentence is quoted: venous thromboembolism (1 paper).